IL4 (interleukin 4)
Diseases named in the same sentence as IL4 in open-access papers (continued):
Sharing a sentence is not in itself a finding about the gene and the disease.
Arthritis (continued). "Nonetheless, this Th1–Th2 paradigm in arthritis susceptibility and resistance in mice has been challenged as C3H/HeJ IFN‐γ and DBA/2J IL‐4 knockout mice developed arthritis of comparable severity to their wild‐type counterparts." (PMID 39396370, 2024). "Statistically significant positive linear correlations were found between the VAS for arthritis and both the serum IL-4 level (r = 0.470; p < 0.001) and the serum IL-21 level (r = 0.403; p < 0.01)." (PMID 37763102, 2023). "When Exo-FBS or Exo-RA was administered to the collagen-induced arthritis model, serum interleukin (IL)-4 and the proportion of Th2 (CD4+CD25+GATA3+) and M2 (CD11c − CD206+ of CD45+CD64+) cells were significantly increased compared to the control group." (PMID 37794417, 2023). "Rats with arthritis showed a marked downregulation of IL-4 (0.405 ± 0.08) and IL-10 (0.309 ± 0.03), indicating that inflammation was successfully induced." (PMID 37111711, 2023). "In the CIA model, continuous administration of IL-4 delayed the onset of arthritis with less severe joint damage and inflammation." (PMID 35163028, 2022). "Regarding the effect of ILC2s on the initiation phase of arthritis, IL-4(+)/IL-5(+)/IL-13(+) ILC2 numbers are increased from the beginning of arthritis in mice." (PMID 35163028, 2022). "For instance, polymeric proanthocyanidin preparation from Serjania schiedeana was shown to reduce joint inflammation and increase the levels of the anti-inflammatory type-2 cytokines IL-4 and IL-10 in the joint and spleen in experimentally induced arthritis." (PMID 36551801, 2022). "The induction of IL-4/IL-5/IL-13(+) ILC2s mitigated arthritis, suggesting the inflammation is regulated by ILC2s." (PMID 35163028, 2022). "Helminth infection by Nippostrongylus brasiliensis, which robustly induced Th2 cells and accumulated eosinophils, reduced a TNFtg arthritis mice model by IL-4/IL-13-induced STAT6 signaling." (PMID 35163028, 2022). "The potential therapeutic value of IL4 has been widely investigated through the local administration of IL4 in arthritis and for chronic inflammation." (PMID 36499452, 2022). "Key type 2 cytokines, like interleukin (IL)-4 and IL-13, but also others such as IL-5, IL-9, IL-25, and IL-33, exert regulatory properties on arthritis, dampening inflammation and inducing resolution of joint swelling." (PMID 35163028, 2022). "J. regia significantly increased the levels of IL-4 in the treatment groups when compared to the positive arthritis control group." (PMID 35422870, 2022). "STAT6 can be activated by IL-4 and IL-13, mainly regulates Th2 differentiation, and inhibits arthritis and inhibits osteoclast differentiation." (PMID 35002715, 2021). "STAT6 plays an essential effect in the differentiation process of Treg cells and can be activated by IL-4 and IL-13 to induce the polarization of macrophages, which is crucial in alleviating the immune activation of arthritis." (PMID 35002715, 2021). "Human studies exploring the therapeutic potential of IL-4 and/or Il-13 cytokines in arthritis are required, as a boosting of anti-inflammatory cytokines seems to be a very promising approach in arthritis." (PMID 34831223, 2021). "IL-4 producing CD8+ T cells have been observed in other models of chronic immune stimulation including arthritis and lymphoma." (PMID 32300344, 2020). "Previous studies have linked IL-4 signaling through IL4Rα to activation of STAT6 pathways and protection in inflammatory models of arthritis." (PMID 30849228, 2019). "IL-4 has been shown to prevent joint damage and bone erosion, to ameliorate arthritis, and to promote tissue repair in CIA mouse models." (PMID 31382595, 2019). "Dietary palmitic acid, an inducer of ER stress and RIDD in NKT cells, and tunicamycin, an activator of ER stress and UPR, inhibit IL-4 and IFNγ in a mouse model of arthritis and leading to reduced antibody induced-joint inflammation." (PMID 30978945, 2019).
Arthritis (continued). "Studies have shown the importance of IL-4 and IL-10 in the control of arthritis because blocking these cytokines has resulted in the accelerated onset of CIA." (PMID 30959746, 2019). "Our findings indicate that pIL-18 gene combined with IL-4 ameliorates arthritis in the CIA mouse by suppression of Th1 and Th17 cytokines and increasing expression of FoxP3 and GATA-3." (PMID 29854762, 2018). "Few studies have explored the role of Th2 cells in RA pathogenesis, but it has been shown that synovial fluid in early arthritis patients who developed RA had elevated levels of the Th2 cytokine interleukin (IL)-4." (PMID 30029616, 2018). "Surprisingly, IL-18 gene therapy combined with IL-4 significantly reduced the mean arthritis score of our murine model." (PMID 29854762, 2018). "The gene expression levels of IL-4 and the Th2 cell transcription factor Gata3 were significantly higher in the pLACK- and rLACK-treated or -vaccinated groups than in the control arthritis group." (PMID 30013572, 2018). "To explore the molecular mechanisms involved in the anti-arthritic effect of N. brasiliensis infection, we challenged Il4−/−Il13−/− (4–13ko) mice and T cell-specific Il4−/−Il13−/− (4–13Tko) mice with N. brasiliensis before the induction of arthritis." (PMID 27273006, 2016). "Treatment with Th2 cytokines (IL-4, IL-10, and IL-13) was tested in many animal models of arthritis based on the Th1 bias of T cells, showing considerable promise." (PMID 27579330, 2016). "At the molecular level, the attenuation of arthritis is dependent on IL-4/IL-13 secretion and STAT6 signalling pathway in haematopoietic cells." (PMID 27273006, 2016). "In this respect, it was shown that BIP, another major RA autoantigen, when injected according to the same procedure than that reported herein, was able to prevent arthritis severity in CIA via the induction of regulatory T cells secreting IL-4." (PMID 26302382, 2015). "The affected 5q LOH interval harbors several cytokine genes (including IL-3, IL-4, IL-5, IL-13, and CSF2), a gene associated with arthritis susceptibility (SLC22A4), a DNA repair gene (RAD50), and a gene that promotes Type 1 interferon responses (IRF1)." (PMID 25107306, 2014). "In the murine model of collagen-induced arthritis, IL-4 is protective against cartilage and bone destruction, and neutralization of IL-4 in the same model results in reversal of arthritis suppression." (PMID 23092393, 2012). "The cytokine IL-10 appears to play a partial role in the A12 prevention of arthritis, whereas IL-4 is more potent." (PMID 22569209, 2012). "In a previous report, we demonstrated that NKT cells promoted antibody-induced arthritis by producing IL-4 and IFN-γ." (PMID 23028952, 2012). "Agonistic monoclonal antibodies to CD40 reduced collagen-induced arthritis, possibly through upregulation of IL-10 and to lesser extent IL-4, indicating an anti-inflammatory role in addition to the pro-inflammatory role of CD40." (PMID 23300544, 2012). "IL-4 is antiangiogenic, and intra-articular injections of the IL-4 gene reduced synovial tissue vessel density, inflammation and bone destruction in rat and mouse models of arthritis." (PMID 21294892, 2011). "Other studies have pointed to a direct role for IL-4 in regulation of tissue destruction in arthritis." (PMID 21294892, 2011). "While the anti-inflammatory activities of IL-4 are well known, restoration and/or enhancement of anabolic factors would form an ideal therapy in arthritis." (PMID 21991344, 2011). "According to Geurts and co-workers, IL-4 can protect cartilage erosion in collagen-induced arthritis and strongly reduces amounts of inflammatory cell influx." (PMID 21991344, 2011). "We previously have demonstrated that exosomes secreted by DC transduced with IL-4 are therapeutic in mouse models of delayed-type hypersensitivity and arthritis." (PMID 20686610, 2010).
Arthritis (continued). "Consistent with our previous findings, mice that received anti-IFN-γ + anti-IL-4 antibodies had more severe arthritis than the anti-IFN-γ alone group." (PMID 19852819, 2009). "Additional experiments were therefore performed to assess the role of IL-4 in mice that were treated with neutralizing antibody to IFN-γ, by neutralizing both endogenous IFN-γ and IL-4 during the early phase of arthritis." (PMID 19852819, 2009). "In order to further elucidate the relative contribution of IL-17 to disease in mice receiving anti-IFN-γ versus anti-IFN-γ + anti-IL-4, we analyzed the correlation between serum IL-17 and arthritis severity." (PMID 19852819, 2009). "In this respect, a beneficial effect of IL-4 has been demonstrated in many experimental model of arthritis." (PMID 19606256, 2009). "In contrast, the augmented arthritis with anti-IFN-γ + anti-IL-4 antibodies was only partially suppressed with anti-IL-17 antibody." (PMID 19852819, 2009). "Daily treatment with IL-4 was reported to reduce all disease parameters in a streptococcal cell wall (SCW) rat arthritis model." (PMID 19606256, 2009). "Increased local levels of IL-1 β, IL-6, TNF-α, MIP-1α, and MIP-2 accompanied the more severe arthritis in IL-4−/− mice." (PMID 19606256, 2009). "IL-4-based interventions can prevent or alleviate joint inflammation and bone damage in multiple animal models of arthritis." (PMID 19852819, 2009). "We have also demonstrated that inappropriate expression of PPT-A and expression of SP in human chondrocytes is correlated with the progression of arthritis and the control of IL-4 expression in that model." (PMID 18320026, 2008). "In the collagen type II-induced arthritis model of mice, chemical sympathectomy before the induction of arthritis decreased disease severity and induced the expression of IL-4 and IL-10." (PMID 16889669, 2006). "In contrast to pro-inflammatory cytokines, IL-4 is one of the major cytokines that are able to protect against severe cartilage destruction during experimental arthritis." (PMID 15642138, 2005). "Induction of immunity is hardly affected by local overexpression, as was shown when injection of AdIL-4 (adenovirus expressing IL-4) in knee joints during arthritis induced by collagen type II markedly increased the amount of inflammatory cells." (PMID 15743487, 2005). "The early expression of IL-4 seems to be important to counteract the dramatic inflammatory response in acute arthritis, as is shown by a protective effect of IL-4 administration in the induction phase of CIA." (PMID 15899031, 2005). "The idea of how to explain the development of arthritis is that inhibition of IL-4 leads to increased secretion of IL-17, which may be responsible for arthritis." (PMID 41481132, 2026). "In zymosan A‐induced arthritis (ZIA) mice, intravenous injection of miR‐21/IL‐4 NPs balanced the M1 and M2 macrophage phenotypes, suppressed inflammatory cell infiltration, and reduced synovial thickening, effectively alleviating arthritis symptoms." (PMID 40040830, 2025). "Walnut leaf ethanolic extract ameliorated acute inflammation and arthritis in rats by increasing the levels of blood IL‐4, besides attenuating TNF‐α, NF‐κB, IL‐6, IL‐16, COX‐2, and prostaglandin E2 (PGE2) amounts in blood, which resulted in reduced paw edema and arthritic development." (PMID 41179368, 2025). "In a rat model of bacterial cell wall-induced arthritis, daily administration of recombinant mouse IL-4 was able to reduce the arthritic index (erythema, edema, and deformity) and reduce the number of inflammatory cells in the peripheral blood and peritoneal cavity." (PMID 36768679, 2023). "A previous study showed that macrophage polarization through IL-4 can occur in joint inflammation." (PMID 35422042, 2022). "In the PIA model, IL-4 knockout mice exhibited an increased frequency of arthritis." (PMID 35163028, 2022). "Activated ILC2S and Th2 cells both produce powerful anti-arthritis cytokines IL-4 and IL-13." (PMID 35928276, 2022).
Arthritis (continued). "Anti-inflammatory cytokines, like IL-13 and IL-4, that were also induced by Zymosan may contribute to tissue repair and quenching of arthritis within 1–2 weeks." (PMID 33878143, 2021). "Results obtained from animal, as well as ex vivo, models of arthritis suggest that the IL-4/IL-13 anti-inflammatory properties might be beneficial in the context of inflammatory arthritis treatment." (PMID 34831223, 2021). "Thus, further studies are needed to assess the potential of different MSC populations in conjugation with IL-4 in the treatment of experimental arthritis." (PMID 31382595, 2019). "The effect might be due to the anti-inflammatory effect of IL-4 exerted at an early stage of arthritis development." (PMID 31382595, 2019). "Contrasting evidence regarding the effect of IL-4 has been reported in a mouse model of arthritis." (PMID 31269967, 2019). "Collectively, treatment with a combined therapy of MSC and IL-4 might have an efficient therapeutic effect on arthritis." (PMID 31382595, 2019). "However only resveratrol showed modulatory effect on the levels of IL-4 and rheumatoid factor in arthritic rats and reduce the inflammatory signs of arthritis and articular damage throughout the time." (PMID 30281626, 2018). "Moreover, combined treatment of empty plasmid vector and recombinant IL-4 had a slight suppressive effect on the macroscopic arthritis score higher than pIL-18 combined with IL-4 therapy." (PMID 29854762, 2018). "The results indicate significant exacerbation of arthritis in mice treated with the control vector or rIL-4 but that coadministration of the control vector and rIL-4 had lower macroscopic arthritis score than the other three groups except pIL-18 combined with IL-4 group." (PMID 29854762, 2018). "However, in other mouse models, the IFN-γ/STAT1 pathway has increased and the IL-4/STAT6 pathway decreased the severity of arthritis." (PMID 27942004, 2016). "In addition, joint levels of TGFβ1, IL-10, IFNγ, IL-4 and IL-17 mRNAs were augmented in WT mice with arthritis." (PMID 22438945, 2012). "Collectively, the in vivo and in vitro experiments confirm that the suppression of arthritis by A12-specific T cells involves active secretion of suppressive cytokines (specifically IL-4 and IL-10), resulting in a downregulation in the inflammatory cytokines IL-17 and IFN-γ." (PMID 22569209, 2012). "While IL-17 is pro-osteoclastogenic in arthritis, IL-4 and IL-13 inhibit osteoclastic differentiation by activation of receptors that decrease RANK formation and by activation of receptors on osteoblasts that decrease RANKL expression but increase osteoprotegerin formation." (PMID 21294892, 2011). "IL-4 and IL-10 on the other hand, have been suggested to ameliorate arthritis." (PMID 21385363, 2011). "Taken together these data suggest that the adenoX-rCB11-A9 therapy may work by inducing a population of T cells to redirect their cytokine response to secrete predominantly IL-4, a cytokine known to ameliorate arthritis." (PMID 20615221, 2010). "Moreover, in protected mice increased levels of IL-4 were present at the time of collagen II injection together with sustained higher IL-4 levels during the course of arthritis development." (PMID 20537152, 2010). "In the PGIA model, arthritis was prevented by IL-4 treatment and exacerbated in IL-4−/− mice." (PMID 19606256, 2009). "In addition, IL-4 reduces bone damage in established CIA, and is necessary for the development of arthritis, possibly due to the important role of IL-4 in B cell activation and antibody production." (PMID 19852819, 2009). "Similar to IFN-γ, evidence for the role of IL-4 in arthritis is complex." (PMID 19852819, 2009). "The antiinflammatory activity of IL-4 was assessed in vivo in several models of arthritis." (PMID 19606256, 2009).
Arthritis (continued). "Interestingly, neutralizing antibody to IL-17 completely abrogated disease in the anti-IFN-γ alone group, whereas anti-IL-17 had only a partial effect on arthritis in the mice that received anti-IFN-γ + anti-IL-4." (PMID 19852819, 2009). "Neutralization of IL-4 led to increased arthritis only in the absence of IFN-γ and was associated with increased bone and cartilage damage without an increase in the levels of IL-17." (PMID 19852819, 2009). "For example, neutralization of IFN-γ or IL-12 or administration of IL-4 during the early phase of disease has been shown to exert a protective effect on the evolution of arthritis, although these strategies were less effective or ineffective if administered during established disease." (PMID 17440622, 2007). "Those authors showed that MSCs treatment induced a more regulatory phenotype with the production of IL-4 and IL-10, but also of IFN-γ, and a systemic decrease of pathogenic antibodies, thus demonstrating the potential value of MSCs treatment in resistant arthritis." (PMID 40493163, 2025). "Furthermore, it has been shown in mouse models that deficiency of IL-4 and STAT6 can result in significant increase in arthritis severity, and that overexpression of IL-4 may protect from cartilage erosions." (PMID 27942004, 2016). "Thus endogenous IFN-γ seems to play a more prominent role than IL-4 in down-regulating arthritis." (PMID 19852819, 2009). "Interestingly, although the anti-IFN-γ group had similar levels of serum and elevated levels of paw IL-17 in comparison to the anti-IFN-γ + anti-IL-4 groups and the arthritis was completely dependent on IL-17, the numbers of Th17 cells in vivo were not increased." (PMID 19852819, 2009). "This OTA-mediated arthritis induced increased IFN-γ and IL-17 levels in the splenocytes, with the IL-4 levels unaffected." (PMID 40423338, 2025). "It was reported that the RIDD of IRE1α pathway inhibits IL‐4 and IFN‐γ production in iNKT cells by promoting t‐bet and gata‐3 mRNA degradation, thereby ameliorating iNKT‐mediated arthritis phenotype." (PMID 38736291, 2024). "Consistent with all of our previous findings, the arthritis control group revealed a significant increase in serum levels of IL-1β, TNF-α, and IL-17 and a significant reduction in the levels of IL-4 in arthritic rats." (PMID 37259429, 2023). "The levels of IL-4, IL-6, MCP-1, and TGF-β successively increase with the progression of joint inflammation." (PMID 37256145, 2023). "The introduction of IL-4 into the joints using viral vectors reduced cartilage destruction, aggrecan degradation, and MMP activity in a mouse arthritis model." (PMID 36768679, 2023). "Statistically significant (P < 0.001) upregulation in IL-4 expression was seen with the piroxicam-, EEJR-, and NHJR-treated groups in comparison with the arthritis control group." (PMID 35422870, 2022). "Methylated BSA/IL-1-induced arthritic mice treated with neutralizing IL-4 antibody showed a 30% reduction in arthritis, suggesting IL-4 regulates CD4 T cell-dependent arthritis." (PMID 35163028, 2022). "Adoptive transfer of ILC2s attenuated murine arthritis severity, and ILC2-derived IL-4/13 inhibited IL-1β and TNFα secretion by macrophages, which indicated the immunoregulatory function of the IL-4/13-producing ILC2 subset in RA." (PMID 33072104, 2020). "In contrast, Th2 (CD4+IL-4+) and Treg cells (CD4+Foxp3+), known to play critical roles counteracting inflammation in arthritis, were increased only in the late stages of arthritis 19,21." (PMID 32332732, 2020). "Lect2 has a protective anti-inflammatory role in arthritis and in the liver Lect2 regulates the homeostasis of NKT cells and also the expression of IL-4 and IFN-γ." (PMID 30559928, 2018). "In the present study, we demonstrated for the first time that IL-18-expressing plasmid gene combined with IL-4 skewed the balance of Th1/Th2/Th17 to a Th2 type and increased GATA-3 and Foxp3 expression on collagen-induced arthritis." (PMID 29854762, 2018).